TERT (telomerase reverse transcriptase)
Diseases named in the same sentence as TERT in open-access papers (continued):
Sharing a sentence is not in itself a finding about the gene and the disease.
tumor (continued). "As seen in the TCGA data, the presence a TERT mutation is also strongly associated with high risk of tumor recurrence, older age, higher MACIS (Metastasis, patient Age, Completeness of resection, local Invasion, and tumor Size) scores, and less-differentiated PTC." (PMID 32849278, 2020). "Besides its canonical role in stabilizing telomeres, telomerase reverse transcriptase (TERT) may promote tumor growth/progression through extra-telomeric functions." (PMID 32722398, 2020). "The presence or absence of the GABPA TF site in TERT promoters of rodents correlates with TERT promoter activity; thus it could determine whether replicative senescence plays a tumor suppressor role in these species, which could be in direct relation with body mass." (PMID 33257697, 2020). "Circulating cell-free TERT mRNA levels have been found to be higher in cancer patients with respect to controls, as well as independent markers of tumor response, and prognostic of disease progression in cancers frequently presenting with high tumor mass, e.g. gastric and colorectal cancer." (PMID 31772219, 2019). "However, the shutting down of TERT expression could, in addition, result from indirect mechanisms through DNA methylation of genes coding for transcriptional regulators as tumor suppressors." (PMID 32082377, 2019). "Other factors than Simpson grade may better predict tumor control rate, e.g. TERT mutation status in the tumor, which was not assessed in this study." (PMID 31477146, 2019). "Thus, high levels of TERT, by stabilizing longer telomeres may indirectly confer cancer cells with an increased resistance to radiotherapy and contribute to tumor progression." (PMID 31772219, 2019). "Although with negative BRAF mutations, we could not exclude that poor tumor behavior is associated with the coexistence of TERT promoter mutation, which was not tested in this study." (PMID 31295281, 2019). "Notably, in the majority of AK and cSCC the expression was restricted to focal areas, indicating that only certain populations of tumour cells may have gained the ability to express substantial level of TERT." (PMID 30884806, 2019). "Moreover, only this double-mutant tumor expressed detectable levels of TERT mRNA." (PMID 31391125, 2019). "MYCN amplification, activating mutations in the ALK receptor tyrosine kinase, TERT rearrangements, inactivating ATRX mutations and dominant negative mutations in PHOX2B are among the most recurrent genetic events that drive oncogenic signaling and tumor formation." (PMID 30952905, 2019). "In addition, plant-derived compounds, for example, BP, the chloroform extract of AS, has been found to inhibit the proliferation of GBM through the down-regulation of TERT and the consequent reduction in TA, leading to tumor apoptosis and senescence in vitro and in vivo." (PMID 30625996, 2019). "The finding that the TERT immunoreactivity in endothelial as well as tumor cells is strictly limited to the neoplastic tissue further supports the idea that TMab-6 detects TERT protein closely bounded to the tumor environment composed of neoplastic tissue and neovasculatures." (PMID 29693015, 2018). "Somatic mutations in the coding region of TERT are not frequent in tumours." (PMID 29751586, 2018). "Therefore, with regard to its low prevalence in PTMC, TERT promoter mutations are unlikely to be reliable molecular markers of tumor aggressiveness/progression." (PMID 30619082, 2018). "Also in Miyauchi's study, no PTMC patients undergoing AS were positive for TERT promoter mutations, even in a subgroup of patients with increased tumor sizes and/or novel lymph node appearance." (PMID 30619082, 2018). "Thus, by slowing proliferation kinetics, TERT inhibition may represent an appealing suppressor strategy of EBV tumor growth." (PMID 29643934, 2018).
tumor (continued). "In fact, even if tumour tissues showed a higher TERT expression and telomere length compared to normal tissues, it is impossible to predict whether and to what extent normal cells would be recognized by TERT-specific T cells." (PMID 29152058, 2017). "The trunk alterations that existed throughout the course were restricted to IDH1 mutation, 1p/19q-codeletion, and TERT promoter mutation, and mutation of the known candidate tumor suppressor genes CIC and FUBP1 were not consistently observed between primary and recurrent tumors." (PMID 28270234, 2017). "Up to 50% of HCCs were previously reported to have TERT promoter mutations, and those studies showed an association of the mutation with certain clinico-pathological variables including age, sex, HBV or HCV infection, α-fetoprotein, tumor sizes/numbers, differentiation status and metastasis." (PMID 28416747, 2017). "However, in two analyzed cases, analysis of regions that showed different histological and imaging features within a tumor demonstrated that TERT promoter mutation was not identical in these regions." (PMID 28270234, 2017). "Compared to TERT promoter mutation-negative patients, TERT promoter mutation-positive patients tended to be older (52.8 vs. 40.4 years, p<0.001), and present with a larger tumor (14.0 vs. 10.0 mm, p = 0.024)." (PMID 27064992, 2016). "Particularly relevant for future applications, this tumor/normal cell lines contains hallmark clinically relevant mutations spanning different mutation classes, including a BRAF V600E SNV, a PTEN 12 kb focal deletion, a TERT dinucleotide block substitution, and a 2 bp small deletion in CDK2NA." (PMID 27094764, 2016). "The small size of the FAST cDNA of only 375 bp, means that large cancer-relevant regulator regions, such as the telomerase reverse transcriptase (TERT) promoter, could be easily accommodated in the vector for tumor-specific regulation of the essential E1 region." (PMID 26986751, 2016). "Thus, TERT promoter mutations are sufficient to overcome the proliferative barrier imposed by telomere shortening without additional tumor-selected mutations." (PMID 26194807, 2015). "This hypothesis would be consistent with our ChRCC WGS analysis examining intra-tumor heterogeneity, where in most cases the TERT promoter SVs were estimated to reside in nearly all of the tumor cells, indicating that these rearrangements represent early events in the cancer." (PMID 25859550, 2015). "Moreover, c-MYC has been described to activate the transcription of TERT, which may contribute to sustaining the proliferation of tumor cells along the cell cycle." (PMID 25889298, 2015). "The switch to immortalisation of the tumour cell is dependent on maintaining the integrity of telomere DNA which forms chromosome ends and is achieved through activation of the telomerase enzyme by turning on synthesis of the TERT gene, which is usually silenced in normal cells." (PMID 24550717, 2014). "However, germ-line mutations at these hotspots have not been observed in various TERT promoter mutation studies which compared paired tumor and normal (blood) tissue isolated DNA, nor were they present in the 1000 Genomes database." (PMID 24260374, 2013). "Although the ability of TERT to promote proliferation has already been proven in various cells, including fibroblasts, epithelial cells, bone marrow mesenchymal stem cells, cancer stem cells and tumor cells, the molecular mechanism remains unclear." (PMID 23946780, 2013). "However, the temporal increase in TERT and TINF2 gene expression and enzyme activity may be linked with growth advantage and increased tumour progression in DFT, as it is in human cancers." (PMID 22952882, 2012). "Both AEI and AI were measured in a series of informative patients using mRNA-encoded cSNPs for SERPINB5 (encoding maspin), TERT (encoding a telomerase subunit) and PRAME (encoding a tumour antigen of unknown function with a highly restricted normal tissue expression pattern." (PMID 16222316, 2005).
tumor (continued). "Among these, HBV integration events near telomerase reverse transcriptase (TERT) gene, a well‐known target of HBV integration, were observed six times in tumor tissues across five patients." (PMID 41536518, 2026). "Third, due to data constraints, we were unable to incorporate additional tumor biomarkers (such as MGMT promoter methylation, TERT, etc.)." (PMID 41008886, 2025). "The use of the RNAscope assay to assess TERT status in FFPE tissue has already been evaluated and validated in tumor samples." (PMID 39858033, 2025). "Next, we analyzed thefrequencies of TERT*C228T in TNC– and TNC+ EV fractions fromplasma samples, where tumor-derived EVs are rare and difficult todetect." (PMID 40056466, 2025). "In our study, we show that TERT amplification is a better predictor of tumor relapse than TPM, extrathyroidal extension, tumor multifocality or tumor size ≥ 5 cm, DMs at diagnosis, and stage at diagnosis I–II vs. III–IV." (PMID 40272676, 2025). "Of note was the fact that the telomerase reverse transcriptase (TERT) gene was differentially expressed (6.41 log2FC), with upregulation in the wild-type PTPN11 tumor samples." (PMID 40149290, 2025). "De facto, when TERT amplification was present in PTC cells, a significant relationship was observed with tumor stage at diagnosis, stage III/IV at last follow-up, and a DOD patient status." (PMID 40272676, 2025). "We then infected cultures of the patient’s tumor cells with recombinant lentiviruses carrying the CDK4R24C, cyclin D1 and TERT genes, and continued to grow them under standard cell culture conditions." (PMID 39878900, 2025). "Correspondingly, H3K27me3 mark deposition was reduced in xenograft HT1080-LT tumours compared to HT1080-ST, supporting that TL-dependent TERT regulation was retained in cells growing in vivo." (PMID 41026782, 2025). "Amplification or epigenetic modification of TERT (rs7734992, 5p15.33) plays a crucial role in ccRCC by maintaining cellular immortality, with HIF1A and EPAS1 regulating TERT expression, enhancing tumour survival under hypoxic conditions." (PMID 41326661, 2025). "TERT-targeting vaccines, such as GV1001 and GRNVAC1, aim to stimulate the immune system to recognize and attack telomerase-expressing tumor cells." (PMID 40243493, 2025). "We next examined the protein levels of c-Myc, TERT, BRAF and PP2Ac in tumor tissues using IHC assays." (PMID 40860184, 2025). "When TERT or GABPB1 were inhibited simultaneously with EGFR, the combination treatment resulted in enhanced inhibition of cell and tumor growth as well as animal survival compared not only to controls but also to any of the single treatments." (PMID 40463649, 2025). "Therefore, TERT + leukocytes may represent the long-term functional reserve of multiple effector cell populations in antitumor immunity, offering significant research value for predicting survival in tumor patients." (PMID 41417416, 2025). "The interplay between TERT, p16 and BAP1 likely creates a permissive environment for tumor development by promoting immortalization (via telomere elongation), evasion of growth suppression (via p16 inhibition) and genomic instability (via BAP1 inactivation)." (PMID 39858033, 2025). "This indicates that the interactions between TERT, TERRA and tumor aggressiveness are complex and the in vivo evidence of correlations between telomere and EMT parameters and the relation to CRC outcome are not well established." (PMID 39222177, 2025). "Furthermore, regardless of concomitant gene alterations, TERT promoter mutation is predominant among older patients and in larger tumors, as well as being strongly associated with extrathyroidal invasion, angiogenesis, tumor recurrence, and mortality." (PMID 39456495, 2024). "We first show that by the addition of the TERT gene, it is possible to immortalize an OSCC tumor-adjacent cell culture." (PMID 38667326, 2024).
tumor (continued). "Recent studies have highlighted the significant prognostic consequences of subtyping molecular pathological markers using tumor samples, such as IDH, 1p/19q, and TERT." (PMID 38982347, 2024). "Consistent with these previous findings, we found that TERT and THBS4 had significantly higher expression levels in tumor than in normal matched samples in all cohorts and that MT1M showed the opposite tendency." (PMID 38985879, 2024). "Despite these differences, all six tumor areas shared copy number changes including a hailstorm on chromosome 22 with congruent CNTs, a CNT upstream of TERT and focal deletion of CDKN2A/B, supporting their common clonal ancestry." (PMID 39034322, 2024). "We further compared clinical characteristics including the tumor grade, 1p/19q co-deletion, MGMT promoter methylation and TERT expression status among different clusters." (PMID 38971948, 2024). "As demonstrated in the current study, DC(I + II) NPs inhibited not only the expression of stemness genes but also the TERT gene and its downstream genes (MMP9 and VEGF2) in both tumor tissues." (PMID 39076585, 2024). "Of note, the low RNA levels of the telomere-related genes (less than five read counts), such as TERT and TERC, in both TCGA-LUAD and TCGA-LUSC tumour samples limited the direct comparison of these genes between these cohorts." (PMID 37079368, 2023). "Out of these 5 hub genes, only CCND1 have high median mRNA expression in normal patients than primary tumor whereas AXL, CDKN2A, TERT, and EZH2 have high expression in the primary tumor." (PMID 36715825, 2023). "In this study, OGM detected MYCN amplification in three cell lines (NB1691, NBLW and SK-N-BE2(C)), a TERT rearrangement in one cell line (GI-ME-N) and an intragenic ATRX deletion in a NB tumour." (PMID 37958407, 2023). "Segmental aberrations in the proximity of TERT were detected through SNP microarray and/or WGS in tumor material from 23 unique patients in total." (PMID 38136279, 2023). "TERT is expressed in all stages of tumor differentiation and is a crucial target for immunotherapy, with CD4 T cells playing a role in combating TERT in cancer." (PMID 37063844, 2023). "Future studies will need to confirm the extent to which B cells present TERT and activate CD4 helper T cells, reshaping the immune response in the tumor microenvironment." (PMID 36909826, 2023). "TERT plays a role in the activity of telomerase and HIF1A in the cellular response to hypoxia, promoting tumour growth." (PMID 37400829, 2023). "One study integrated MRI and clinical data (age, gender, weight, and tumor size) to predict tumor genotype of four biomarkers (MGMT, 1q/19q, IDH, and TERT) and OS time." (PMID 36672494, 2023). "Two non-tumor cell lines (HMEC and MCF-10F) expressed TERT at very similar levels, whereas expression in Hs 578Bst was below detection, and MCF-10A expressed TERT at a ≈70-fold higher level than the average of HMEC and MCF-10F." (PMID 36768147, 2023). "In addition, a tumor-burden mice model by cell transplantation further demonstrated the promotion of tumor growth by pMX-CCAT2 in vivo, which was associated with increased levels of cell proliferation factors (Ki67 and CCND1) and cell stemness genes (h-TERT, NANOG, SOX2, KLF4 and OCT4)." (PMID 36672487, 2023).
tumor (continued). "Case 66R3C, with strong signal in both Phi29+ and Phi29−, displayed long telomeres in the tumor and presented a confident score of 0.97 for methylation subclass “ALT/TERT TMM positive”, thus supporting the presence of active TMM." (PMID 38136279, 2023). "Therefore, in light of the possible integration of TERT inhibitors in chemotherapeutic regimens, we evaluated the possible therapeutic application of the combined treatment with TERT inhibitors and antineoplastic drugs frequently used to treat B-cell malignancies to counteract tumour growth in vivo." (PMID 37345011, 2023). "Similar to TERT promoter GA frequencies, CCND1 amplification was most frequently detected in the penSCC (15%) and vulSCC (18%) tumor." (PMID 35881043, 2022). "It plays an important role in the occurrence and development of various human tumor diseases, and studies have shown that NFAT5 can regulate the transcription of the mouse TERT gene and promote the expression of TERT." (PMID 35739589, 2022). "PEGylated liposomes conjugated with antibodies against TfR and HIR (PILPs) were loaded with siRNAs directed against the mRNA of telomerase reverse transcriptase (TERT) and EGFR, both involved in tumor growth." (PMID 36297407, 2022). "We also observed that one of the four tumours from disease‐free patients with long follow‐ups and short telomeres showed elevated TERC expression and TERT copy gain." (PMID 35979662, 2022). "Here, we show that, contrary to what it has been shown in other tumor types, multiple factors of the ETS family are able to control TERT transcription and they do so in both the presence and absence of promoter mutations." (PMID 35053525, 2022). "TERT expression increased significantly in HCT116 and A549 tumours extracted from mice treated with C‐1305 + PTX when compared to all other treatment groups." (PMID 35701366, 2022). "When the NGS analysis was performed in parallel on the corresponding cancer tissue, we observed that the mutational status of NF1 and TERT in the EV correlated with that from matched tumor tissue (8/10 and 2/10 patients for NF1 and TERT, respectively)." (PMID 36289852, 2022). "UroAmplitude identified TERT, PLEKHS1, FOXQ1, KMT2C, and ERBB2 somatic events in urine collected prior to resection of an HG T1 multifocal tumor." (PMID 36233691, 2022). "We detected 44 HBV integration breakpoints in 23 (57.5%) of the primary tumor samples and 45 HBV integration breakpoints in 24 (60%) of the recurrent tumor samples, including recurrent HBV integration events in TERT, a well-known HCC driver gene." (PMID 35078970, 2022). "The subcutaneous injection of the TERT (572Y) peptide followed by the subcutaneous administration of the TERT peptide was aimed to elicit a specific and possibly optimal cytotoxic T-cell (CTL) response against hTERT-expressing tumor cells." (PMID 36361634, 2022). "Distributions of tumor MGMT status and EGFR, TERT, and IDH1 genomic alterations observed in the current study are consistent with those reported in the current literature." (PMID 34510238, 2022). "The TERT promoter region has been identified as the most frequent site of HBV insertion in HCC (38.5%), but it is rarely observed in non-tumor liver tissues (3%)." (PMID 36358677, 2022). "The expression levels of oncogenes or tumor-related genes, such as BRAF, NOTCH3, and TERT, were higher in tumor tissues compared with paired normal tissues." (PMID 36092890, 2022). "However, GABPA and GABPB1 stimulate TERT transcription, but several lines of evidence suggest that they may serve as tumor suppressors in other cancer types regardless the presence or absence of TERT promoter mutations." (PMID 36713366, 2022).